LINC00824 (long independently transcribed non-coding RNA 824)
Synonyms: formerly LINC01263
Gene: Long non-coding RNA gene on chromosome 8 (128,405,269 to 128,564,690, reverse strand). Ensembl gene ENSG00000254275.
Diseases named in the same sentence as LINC00824 in open-access papers:
LINC00824 is named in the same sentence as 3 diseases in open-access papers, as found by Europe PMC text mining. Sharing a sentence is not in itself a finding about the gene and the disease. The quoted sentences say what the papers report.
allergic disease (1 paper, 2022). An immune response that occurs following re-exposure to an innocuous antigen, and that requires the presence of existing antibodies against that antigen. "Our study newly identified six loci associated with allergic diseases (MIIP, CXCR4, SCML4, CYP1B1, ICOS and LINC00824) and four pleiotropic loci associated with both autoimmune and allergic diseases (PRDM2, G3BP1, HBS1L and POU2AF1)." (PMID 35753705, 2022).
cancer (1 paper, 2022). A tumor composed of atypical neoplastic, often pleomorphic cells that invade other tissues. "Among these, LINC00824 (PVT1), which is adjacent to c-MYC gene and frequently upregulated in many cancers, was identified as a BRD4 target." (PMID 35399501, 2022).
LINC00824 also shares sentences with these, for which no sentence is quoted: hypothyroidism (1 paper).